CAST (calpastatin )
Synonyms: BS-17; MIR583HG; PLACK
Gene: Protein-coding gene on chromosome 5 (96,247,756 to 96,779,595, forward strand). Ensembl gene ENSG00000310517.
Pathways (Reactome):
Disease: Deregulated CDK5 triggers multiple neurodegenerative pathways in Alzheimer's disease models
Extracellular matrix organization: Degradation of the extracellular matrix
Gene Ontology:
Molecular function: cadherin binding; calcium-dependent cysteine-type endopeptidase inhibitor activity; protein binding; RNA binding; endopeptidase inhibitor activity
Biological process: negative regulation of type B pancreatic cell apoptotic process; presynaptic active zone organization
Cellular component: cytosol; endoplasmic reticulum; membrane; plasma membrane; cytoplasm
Homologues: Orthologues: chimpanzee CAST (98% identical), macaque CAST (87% identical), dog CAST (77% identical), rabbit CAST (74% identical), rat Cast (65% identical), mouse Cast (58% identical), tropical clawed frog cast (37% identical), zebrafish cast (24% identical).
Diseases named in the same sentence as CAST in open-access papers:
CAST is named in the same sentence as 151 diseases in open-access papers, as found by Europe PMC text mining. Sharing a sentence is not in itself a finding about the gene and the disease. The quoted sentences say what the papers report.
Obesity (9 papers, 2006 to 2025). Accumulation of substantial excess body fat. "Among them, genes of the glucose metabolism, such as CAPN10, encoding for calpain, a calcium-sensitive cysteine protease associated with type 2 diabetes, and its inhibitor CAST, involved in obesity-induced AT inflammation, were up-regulated in this subject group." (PMID 30838002, 2019). "Despite that this method has not been used elsewhere and the lack of alternative methods for subcongenic strains, the results obtained by this approach suggest further investigation of the “Gnas imprinted locus” and the effects that CAST alleles have on obesity at this locus." (PMID 25613955, 2015). "Further studies are warranted to understand the mechanisms by which (i) calpain activation promotes PCK-1 gene expression and activity and (ii) CAST overexpression leads to insulin resistance in long term obesity." (PMID 29089532, 2017). "To investigate the role of calpains in diet-induced obesity, we used CAST overexpressing transgenic mice to inhibit activities of both calpain-1 and -2." (PMID 29089532, 2017). "Using CAST transgenic mice, we examined the role of calpains in adipose tissue remodeling during diet induced-obesity." (PMID 29089532, 2017). "CAST Tg overexpression mediated calpain inhibition significantly suppressed obesity induced apoptotic cell death, pro-apoptotic genes (Bid, Bax, and Bcl10), and adipose tissue macrophage accumulation." (PMID 29089532, 2017). "CAST overexpression significantly attenuated obesity-induced inflammatory responses in adipose tissue." (PMID 29089532, 2017). "Growth and meat quality traits were evident through CAST (calpastatin, regulating muscle tenderness), FTO (fat mass and obesity‐associated gene, impacting fat deposition), GHR (growth hormone receptor) and MTOR (mechanistic target of rapamycin, controlling muscle protein synthesis)." (PMID 40859468, 2025). "In the Ossabaw swine model of obesity there was an up-regulation of 186 PVAT-derived proteins associated with increased coronary contractility and these included transforming protein RhoA and calpastatin." (PMID 29479319, 2018). "Interestingly, CAST overexpression showed a slight and significant improvement in the early stage (5 weeks) of obesity, which disappeared in the late stage of obesity (16 weeks)." (PMID 29089532, 2017). "The same study also reported that obesity leads to a dysregulation of calpastatin." (PMID 29234017, 2017). "The observed reduction in adipocyte apoptosis, in addition to, impaired macrophage migration, and accumulation upon CAST overexpression may well correlate with the observed reduction of obesity-induced adipose tissue inflammation." (PMID 29089532, 2017). "To examine the effect of CAST overexpression on HFD-induced glucose tolerance, we performed glucose tolerance test (GTT) and insulin tolerance test (ITT) during an early (5 or 6 weeks post diet) and late (15 or 16 weeks post diet) stage of obesity." (PMID 29089532, 2017). "However, since numerous obesity QTL have been found on MMU2, some of which were discovered in B6 by CAST crosses, we chose to measure dissected fat pad weights as a more sensitive measure of adiposity." (PMID 16670015, 2006). "In addition, QTLs for obesity and related traits identified from CAST/EiJ and other strains have so far not been fine-mapped to the Pbwg1.5 region on mouse chromosome 2." (PMID 25398139, 2014).
breast carcinoma (7 papers, 2012 to 2025). "To elucidate the mechanisms underlying TXNIP’s antitumor effects in breast cancer cells, we conducted co-immunoprecipitation and proteomic analyses that revealed calpastatin (CAST) as a novel TXNIP-interacting protein in MDA-MB-231 and HCC-1954 cells." (PMID 40175348, 2025). "Low calpastatin expression was significantly associated with adverse breast cancer-specific survival of the inflammatory breast cancer patients (P=0.020), as was low calpain-1 expression (P=0.003)." (PMID 27323818, 2016). "In inflammatory cases, high calpain-1 and high calpastatin expression is associated with improved breast cancer-specific survival." (PMID 27323818, 2016). "An association between low cytoplasmic calpastatin expression and the presence of lymphovascular invasion, encompassing invasion of both lymphatic and blood vessels has been reported in breast cancer." (PMID 23140395, 2012). "While high calpain-2 and low CAST expression was associated with improved survival in patients with non-inflammatory breast cancer treated with neoadjuvant chemotherapy, high calpain-1 and high CAST expression in the inflammatory group was associated with improved breast cancer survival." (PMID 37795261, 2023). "High caspase-3/high calpain-1, high caspase-3/high calpain-2 and high caspase-3/low calpastatin expression significantly associated with adverse breast cancer-specific survival in the total patient cohort; and combinational caspase-3/calpain-1 has important prognostic value in basal-like patients." (PMID 27798717, 2017). "The aim of this study was to investigate the expression of calpain-1, calpain-2 and calpastatin in diagnostic, core biopsy specimens from women with large but operable primary breast cancer who were subsequently treated with neoadjuvant chemotherapy prior to surgical excision of residual tumour." (PMID 27323818, 2016). "The expression of calpain-1, calpain-2 and calpastatin was determined in diagnostic core biopsy samples taken from patients with large but operable breast cancer or locally advanced breast cancer who subsequently received neoadjuvant chemotherapy prior to surgical resection." (PMID 27323818, 2016). "Furthermore, low calpain-1 and calpastatin expression are associated with adverse survival of patients with inflammatory large but operable breast cancer." (PMID 27323818, 2016). "Furthermore, low expression of calpastatin and calpain-1 is significantly associated with adverse breast cancer-specific survival in inflammatory large but operable primary breast cancer." (PMID 27323818, 2016). "Conversely, in breast cancer patients, CAST mRNA and protein levels show an inverse relationship with the poor prognostic indicator of lymphovascular invasion, indicating possible anti-tumor activity." (PMID 40175348, 2025). "Only caspase-3/calpastatin expression was identified as an independent factor for breast cancer-specific survival from multivariate analysis." (PMID 27798717, 2017). "The significance of caspase-3/calpastatin for breast cancer-specific survival was retained in multivariate analysis (HR 1.241, 95% CI 1.053–1.462; P = 0.01), when considering previous confounding factors." (PMID 27798717, 2017). "The calpain system in general has been implicated in tumour progression, including altering cellular migration, survival and apoptosis; and expression of calpain-1, calpain-2 and calpastatin have been shown to be important in breast cancer." (PMID 25539577, 2014). "Altered expression of the catalytic subunits of μ-calpain and m-calpain, and calpastatin has been described in a number of tumour types including breast cancer." (PMID 23140395, 2012). "Might the subcellular localization of calpain isoforms, instead of the expression levels of calpains or calpastatin, have a prognosis value in breast cancer?" (PMID 37795261, 2023).
breast carcinoma (continued). "Patients with high caspase-3/high calpain-1 expression, high caspase-3/high calpain-2 expression, high caspase-3/low calpastatin expression, or high caspase-8/low calpain-1 expression had significantly worse breast cancer-specific survival (P = 0.005, 0.049, 0.02, and 0.02 respectively)." (PMID 27798717, 2017). "In conclusion, high calpain-2 and low calpastatin expression is associated with improved breast cancer-specific survival in non-inflammatory large but operable primary breast cancer treated with neoadjuvant chemotherapy." (PMID 27323818, 2016). "This study has demonstrated that low expression of calpain-2 and high expression of calpastatin determined in diagnostic core biopsy samples is significantly associated with adverse breast cancer-specific survival in non-inflammatory large but operable primary breast cancer." (PMID 27323818, 2016). "In addition to identifying the novel interaction between CAST and TXNIP, our study revealed that overexpressing TXNIP increases IL-24 levels while knocking down TXNIP decreases IL-24 expression in breast cancer cells." (PMID 40175348, 2025). "The expression of calpain-1, calpain-2 and calpastatin was determined using immunohistochemistry on core biopsy samples, in a cohort of large but operable inflammatory and non-inflammatory primary breast cancer patients treated with neoadjuvant chemotherapy." (PMID 27323818, 2016). "It is interesting to note that the current results show a high frequency of calpastatin expression within the nucleus, that has not previously been observed in other tumour types, such as breast cancer." (PMID 23140395, 2012).
Alzheimer disease (6 papers, 2008 to 2024). A progressive, neurodegenerative disease characterized by loss of function and death of nerve cells in several areas of the brain leading to loss of cognitive function such as memory and language. "Damaging calpain overactivation has been associated with the pathogenic reduction of the natural endogenous calpain inhibitor calpastatin in vivo models of Alzheimer’s disease, amyotrophic lateral sclerosis and Huntington’s disease." (PMID 35126465, 2021). "By contrast an increase in calpain in Alzheimer's disease brain, the calpastatin expression is markedly reduced in the neocortex in Alzheimer's disease." (PMID 18706097, 2008). "Further, previous studies have demonstrated an inverse correlation between calpain and calpastatin expression levels in the brain of Tg2576, a mouse model of Alzheimer's disease." (PMID 18706097, 2008).
cardiac hypertrophy (6 papers, 2013 to 2025). "It has been reported that transgenic over-expression of CAST significantly attenuated angiotensin II-induced myocardial hypertrophy, diabetes-related myocardial hypertrophy and fibrosis and endotoxaemia-induced myocardial dysfunction." (PMID 25786109, 2015). "Several preclinical studies using transgenic models with an altered calpain/calpastatin system and pharmacological inhibitors support the contribution of calpains to the development of cardiac hypertrophy and its progression to adverse remodeling and cardiac dysfunction." (PMID 35456920, 2022). "Providing further evidence of calpain contribution to myocardial remodeling, the inhibition of calpain by deletion of Capn4 prevented hypertrophy in a model of pulmonary hypertension, and calpastatin overexpression reduced myocardial hypertrophy and fibrosis in a mouse model of type 1 diabetes." (PMID 35456920, 2022). "By contrast, inhibition of calpain by using the same calpastatin overexpressing mouse strain prevented cardiac hypertrophy induced by chronic infusion of angiotensin II through a mechanism independent of NFAT activation but dependent on the translocation to the nucleus of NF-κB." (PMID 35456920, 2022). "Moreover, some of these genes, including the ones coding for catalase and calpastatin, have been involved in the development of cardiac hypertrophy and could therefore provide the link between Cavβ2 expression and this pathology." (PMID 34307509, 2021). "Consistent with this scenario, the attenuation of calpain activity by constitutive calpastatin overexpression or Capn4 genetic deletion reduced the activation of the NFAT pathway and attenuated myocardial hypertrophy in a mouse model of type 1 diabetes." (PMID 35456920, 2022). "In CAST OE mice, basal phenotype and AngII-induced myocardial hypertrophy were comparable with non-induced controls (mean heart to body weight ratios ± SD in milligrams per gram: CAST OE, 4.8 ± 0.4; CAST OE + AngII, 7.1 ± 0.5; non-induced, 4.9 ± 0.4; non-induced + AngII, 7.2 ± 0.4)." (PMID 40025327, 2025). "Globally, these studies demonstrate that calpain overactivation is a general trait of myocardial hypertrophy, regardless of the triggering stimulus, and it is a consequence of calpain overexpression, altered cellular Ca2+ dynamics, and/or reduced calpastatin inhibitory capacity." (PMID 35456920, 2022).
neuroblastoma (5 papers, 2013 to 2025). Neuroblastoma (NB) is the most common solid, extracranial childhood tumor. "Here, the effect of 8-hydroxyquinoline and derivatives (5-chloro-7-iodo-8-hydroxyquinoline or clioquinol and 8-hydroxy-5-nitroquinoline or nitroxoline) on calpain-dependent (calpain-calpastatin) pathways in human neuroblastoma (SH-SY5Y) cells was investigated." (PMID 27635352, 2016). "Altered expression levels for both calpain and calpastatin proteins were also described during human neuroblastoma cell differentiation to Schwann and neuronal cells." (PMID 23717474, 2013). "In neuroblastoma cells treated with H2O2, calpastatin is able to alleviate disturbances in mitochondrial dynamics by decreasing mitochondrial fission protein (Fis-1 and Drp-1) levels." (PMID 34365571, 2022). "In the neuroblastoma cells SH-SY5Y, an upregulation of calpastatin was reported to result in the inhibition of calpain, a proteolytic enzyme involved in many biological processes including migration." (PMID 28418857, 2017). "Consistent with our observations in MYCN-amplified neuroblastoma cells, the cytotoxic effects of Cas9D10A targeting an amplified locus were significantly reduced at many doses in the presence of PARP inhibitors or calpastatin." (PMID 40456709, 2025). "Finally, we assessed whether the cellular toxicity of Cas9D10A-induced DNA damage could be attenuated in the same manner as the MYCN-amplified neuroblastoma cell lines by treating BT-474, NCI-H716, or NCI-H2170 cells with either rucaparib (PARPi) or calpastatin (CAST) in the presence of Cas9D10A." (PMID 40456709, 2025).
retinal degeneration (5 papers, 2012 to 2023). Degeneration of the retina. "CAST/EiJ and NOD.NOH-H2nb1 genetic backgrounds also confer resistance to rd7 associated retinal degeneration; however, genetic modifiers on these backgrounds mapped to independent chromosomal locations." (PMID 24498227, 2014). "Our findings are consistent with the original characterisation of Crb1RD8/RD8 mice, which demonstrated that the retinal degeneration is strongly modulated by backcrosses into C57Bl/6, CAST/EiJ or C3HfB6/Ga mice." (PMID 22545116, 2012). "Ectopic ribbon synapses in the ONL have been observed in a mouse model of retinitis pigmentosa, as well as in a number of mutant mouse lines, including the CAST KO and LKB1 cKO, suggesting an association of these aberrant structures with retinal degeneration and visual defects." (PMID 37108413, 2023). "Specifically, complete suppression of rd7 retinal degeneration was observed in outcrosses of B6.Cg-Nr2e3rd7/rd7 mice to AKR/J, CAST/EiJ or NOD.NOH-H2nb1 mice and several modifier loci that were unique for each strain were identified." (PMID 24498227, 2014). "In S334ter and P23H RHO rats, strong activation of calpain and poly(ADP-ribose) polymerase (PARP), concomitant with calpastatin downregulation, increased oxidative DNA damage and accumulation of PAR polymers was strictly correlated with the temporal progression of retinal degeneration." (PMID 24378535, 2014).
glioblastoma (4 papers, 2018 to 2024). The most malignant astrocytic tumor (WHO grade IV). "CAST promotes GC cell responses to 5‐fluorouracil by regulating the thymidylate synthase‐5‐fluoro‐dUMP complex, but promotes radiation resistance in Glioblastoma multiforme cells by enhancing activity of calpain proteases." (PMID 32939931, 2020).
Huntington disease (4 papers, 2015 to 2021). Huntington disease (HD) is a rare neurodegenerative disorder of the central nervous system characterized by unwanted choreatic movements, behavioral and psychiatric disturbances and dementia. "Genetic knockdown of calpain or overexpression of the calpain inhibitor calpastatin increased autophagy and improved motor signs and delayed onset of tremors in a mouse model of Huntington disease (HD)." (PMID 31936109, 2020). "Furthermore, we demonstrate that, overexpression of the calpain inhibitor, calpastatin, increases autophagosome levels and is protective in a mouse model of Huntington's disease, improving motor signs and delaying the onset of tremors." (PMID 25257175, 2015).
cardiomyopathy (3 papers, 2017 to 2025). A disease of the heart muscle or myocardium proper. "However, in addition to our cases, there have been three reports of DCM in cases with PLACK syndrome supporting an association of mutated CAST with recessive cardiomyopathy." (PMID 41300744, 2025). "For instance, CAST[F1] Taz-KO mice had severe cardiomyopathy but normal treadmill endurance, whereas WSB[F1] Taz-KO mice had significantly impaired treadmill endurance and mild, late-onset cardiomyopathy." (PMID 40326536, 2025). "In animal models, studies have supported a biologically plausible link between calpain–calpastatin system dysregulation and cardiomyopathy." (PMID 41300744, 2025). "For example, whether overexpression of calpastatin, or application of calpeptin or MDL-28170, or apocynin would allow animals to withstand HFD-induced cardiomyopathy needs to be carefully evaluated." (PMID 28887535, 2017).
gastric cancer (3 papers, 2022 to 2025). A primary or metastatic malignant neoplasm involving the stomach. "In gastric cancer, elevated CAST expression is significantly linked to reduced overall survival, suggesting its tumor-promoting potential." (PMID 40175348, 2025). "In our present study, we demonstrated that CAST is an oncogene associated with Lgr5 in gastric cancer via the WNT signaling pathway." (PMID 35625600, 2022). "CAST is a potential cancer promoter in macrophage-infiltrated gastric cancer and regulates LGR5 expression." (PMID 41194856, 2025).
hepatocellular carcinoma (3 papers, 2017 to 2023). A malignant tumor that arises from hepatocytes. "The results confirm that calpain-1 is overexpressed and calpastatin is reduced in the muscle of rats implanted with the AH-130 hepatoma, and show for the first time that the Ca2+-dependent proteolytic system is overactivated also in the C26-bearing mice." (PMID 28469577, 2017). "screened potential autoantibody-based markers for hepatocellular carcinoma (HCC) and found that the AUC of an immunodiagnostic model including 6 TAAbs (RAD23A, CAST, RUNX1T1, PAIP1, SARS, PRKCZ) were 0.835 and 0.788 in the training and validation sets, respectively." (PMID 37251926, 2023).